IL1B (interleukin 1 beta)
Diseases named in the same sentence as IL1B in open-access papers (continued):
Sharing a sentence is not in itself a finding about the gene and the disease.
cardiovascular disease (continued). "Pro-inflammatory cytokines such as TNF, IL-1β, and IL-6, secreted by monocytes, enhance their migratory potential towards tissue sites of inflammation and are associated with an increased risk of cardiovascular disease in patients with CKD." (PMID 38558798, 2024). "IL-1β might be considered as a pharmacological target for preventing cardiovascular diseases caused by cigarette smoking." (PMID 36791122, 2023). "The expression of pro-inflammatory cytokines, such as TNF-α, IL-1β and IL-6, has been found to be up-regulated in the large elastic arteries of old mice and humans, and may therefore be associated with age-related cardiovascular disease." (PMID 36465181, 2022). "Evidence for pyroptosis in I/R injury comes from studies with caspase-1 inhibitors, which reduce cardiac I/R injury 36 and the IL-1β inhibitor, Canakinumab, which in humans has shown to result in a 15% reduction in mortality associated with all cause cardiovascular disease." (PMID 33878183, 2022). "All these findings suggested that IL-1β could serve as a promising therapeutic target for the reduction of cardiovascular disease risk." (PMID 33562334, 2021). "This study aimed to investigate the linkage between adipocytokines and insulin with the cardiovascular disease risk, with particular reference to the adipokines galectin-3, plasminogen activator inhibitor-1, and interleukin-1-beta, C-reactive protein, and monocyte chemoattractant protein." (PMID 32290863, 2020). "Moreover, IL-1β promoted the thrombus formation via NET-associated tissue factor during atheroembolic events during cardiovascular diseases." (PMID 32498376, 2020). "Interestingly, IL-1α and IL-1β are both known to be critical paracrine (and endocrine) mediators of inflammation linked to lung and cardiovascular disease." (PMID 32316988, 2020). "Given the central role of NLRP3/IL-1β in cardiovascular diseases, it is likely that the NLRP3 inflammasome and IL-1β signalling also contribute to the cardiac involvement in MIS-A." (PMID 39775145, 2025). "A possible explanation lies in the fact that regular PA stimulates the release of myokines, which regulate inflammatory markers such as TNF-α, IL-6, IL-1β, and CRP, all of which are associated with cardiovascular disease." (PMID 40868631, 2025). "The CANTOS results confirmed the potential to improve the outcome of patients post-MI by targeting the function or production of IL-1β, highlighting the crucial role of IL-1β in the progression of cardiovascular diseases." (PMID 40079000, 2025). "In old RMs, EAA in the spleen was directly related to the plasma levels of IL-1B, a key mediator of inflammatory response (P = 0.038), and IL-12, a biomarker of cardiovascular disease and promoter of spleen hematopoiesis (P = 0.032)." (PMID 40662355, 2025). "Gla-rich protein (GRP) and interleukin-1β (IL-1β) are recognized as reliable biomarkers for evaluating inflammation and are effective predictors of cardiovascular disease." (PMID 40241989, 2025). "Despite being mechanistically linked to cardiovascular disease, TNF-α and IL-1β showed weaker and less reliable correlations." (PMID 41011058, 2025). "In fact, recent studies have highlighted the potential of both TNF-α and IL-1β as therapeutic targets for the prevention of cardiovascular diseases." (PMID 39877523, 2025). "By identifying Ap4 as a danger signal for IL-1β release, this study enhances our understanding of “inflammaging” as a driver of cardiovascular disease." (PMID 39984847, 2025). "As a prominent inflammatory cytokine, IL-1β contributes significantly to the development of cardiovascular disease." (PMID 40427511, 2025). "Recent studies have highlighted pyroptosis-related molecules—particularly gasdermin D (GSDMD), interleukin-1β (IL-1β), and interleukin-18 (IL-18)—as potential biomarkers for cardiovascular diseases." (PMID 40832143, 2025).
cardiovascular disease (continued). "As an inflammatory cascade reaction, inflammatory factor IL-1β plays a major regulatory role in the occurrence and development of various cardiovascular diseases." (PMID 39874368, 2025). "Inhibition of inflammasomes or IL-1β has shown promise as a therapeutic target in cardiovascular diseases, including CAD." (PMID 39039680, 2024). "Previous studies have demonstrated a relationship between IL-1β and elastin metabolism in the development of cardiovascular disease." (PMID 39232217, 2024). "Being the most extensively studied inflammasome among NLR family members, NLRP3and its downstream cytokine IL1β play a major role in cardiovascular disease by regulating the innate immune response, as we and others reported previously." (PMID 38281937, 2024). "This systematic review aims to evaluate the current evidence on the roles of IL-6 and IL-1β in cardiovascular diseases." (PMID 39057626, 2024). "Future research should focus on further elucidating the mechanistic pathways through which IL-6 and IL-1β contribute to cardiovascular disease progression." (PMID 39057626, 2024). "IL-1β blockade has been shown to reduce cardiac morbidity in patients with established cardiovascular disease." (PMID 38512880, 2024). "Our review highlights the significant roles of IL-6 and IL-1β in the pathogenesis and progression of cardiovascular diseases." (PMID 39057626, 2024). "Perhaps the pharmacological inhibition of IL-1β will represent an effective therapeutic tool for both cardiovascular disease and kidney fibrosis." (PMID 38615014, 2024). "Although the higher levels of IL-1β were observed mainly for the cardiovascular disease group, the concentration of this cytokine compared to the other cytokines was extremely elevated in all disease groups, including the no record group." (PMID 39328992, 2024). "As drugs targeting IL-1β and IL-6 are available for use in cardiovascular disease treatment, further investigation of these interleukins in the disease manifestation and progression in adult human tissue and human disease models is critical." (PMID 38776872, 2024). "This trial highlighted the potential of targeting IL-1β as a therapeutic strategy in cardiovascular disease management." (PMID 39057626, 2024). "Among the markers of inflammation associated with cardiovascular diseases in pre-dialysis CKD patients, the role of cytokines such as interleukin 1 beta (IL-1 beta) is known, but their relationship with NT-proBNP or hormonal status has not been studied." (PMID 38891884, 2024). "Since inflammation plays a crucial role in cardiovascular diseases, we further utilized ELISA to measure the levels of IL-6, IL-1β, and TNF-α in the supernatant of cells after cGAS knockdown." (PMID 38124089, 2023). "We first assessed CAEC pro-inflammatory cytokine production for IL-6, TNF-α, IL-18 and IL-1β, which are four important players for the development of cardiovascular diseases together with the anti-inflammatory cytokine IL-10." (PMID 36992409, 2023). "IL-1β and IL-18 persist in damage to endothelial cells, which exacerbates synovial inflammation and cardiovascular disease in RA patient." (PMID 37063906, 2023). "The IL-1β blockade of canakinumab impairs inflammation in blood vessels in patients with cardiovascular disease and reduced recurrent cardiovascular events." (PMID 36766606, 2023). "Compelling evidence of a role for IL-1β signaling in cardiovascular disease has also been presented." (PMID 36782020, 2023). "IL-1β is a potent proinflammatory cytokine that has been responsible for chronic inflammatory conditions such as cardiovascular disease, coronary artery lesions, and vasculopathy, relevant to the pathogenesis of KD." (PMID 35615376, 2022). "Once activated, it can trigger and amplify sterile inflammatory responses by activating and releasing IL-1β, which has been reported to involve in the pathophysiology cardiovascular disease." (PMID 35910846, 2022).
cardiovascular disease (continued). "In our study, the higher levels of TNF-α, IL-1β, and IL-6 in PBMCs from AP individuals were also accompanied by the upregulation of several cardiovascular disease biomarkers like adiponectin and angiogenin." (PMID 35300329, 2022). "Robust evidence has demonstrated a critical role for the NLRP3 inflammasome in the pathophysiology of various cardiovascular diseases (CVDs) owing to its ability to secrete the pro-inflammatory cytokines IL-1β and IL-18." (PMID 35806076, 2022). "In light of recent trials, namely the CANTOS study, showing the enormous potential of anti-inflammatory therapies and in particular those targeted to IL-1β, a change in therapeutical management of cardiovascular diseases is coming about." (PMID 35204152, 2022). "Some authors reported that increasing in serum levels of some pro-inflammatory cytokines (IL-1b, IL-8, and TNF-α) goes along with the increment of cardiovascular diseases risk." (PMID 36096730, 2022). "The CANTOS trial highlighted the importance of direct anti-inflammatory therapies targeting the NLRP3 inflammasome-derived inflammatory cytokine IL-1β in secondary cardiovascular disease prevention." (PMID 36111168, 2022). "Rilonacept, a decoy receptor that binds IL-1β and IL-1α, also displayed potential therapeutic effects in cardiovascular diseases, but there was only one clinical trial on cardiovascular diseases, and the subjects were patients with recurrent pericarditis." (PMID 36111168, 2022). "In addition to the primary findings of CANTOS where IL-1β repression resulted in a reduction in cardiovascular morbidity and mortality, residual inflammation after treatment with canakinumab (assessed through IL-6 and IL-18 tertiles) also associated with incident cardiovascular diseases." (PMID 35911546, 2022). "miR-34a influences lipid metabolism by inhibiting the Sirtuin 1 (SIRT1) pathway as well as stimulating pro-inflammatory cytokines such as IL-1b, IL-7A CRP and TNF-α which are strongly associated with cardiovascular diseases." (PMID 36071532, 2022). "In line with the promising genetic findings, randomized conrolled trials (RCTs) have been conducted to assess the effects of IL-1β inhibitors in treating cardiovascular disease." (PMID 35292824, 2022). "IL-1β is an important proatherogenic factor, and a recent study revealed that targeting IL-1β using an IL-1β-neutralizing antibody has proven beneficial for cardiovascular diseases in the Canakinumab Anti-Inflammatory Thrombosis Outcomes Study (CANTOS) trial." (PMID 35464766, 2022). "Of course, IL-1β and IL-18 have great prospects as biomarkers for predicting the occurrence of cardiovascular diseases." (PMID 35647057, 2022). "Further, apabetalone diminished the production of pro-inflammatory cytokines (TNF-α and IL-1β) in hyper-responsive monocytes isolated from diabetic patients with cardiovascular disease." (PMID 33919584, 2021). "The effects of resveratrol are indicated by decreased serum levels of inflammatory cytokines such as TNF-α, IL-1β, and IL-6, and suppression of the NF-κB pathway for cardiovascular diseases in rats." (PMID 34287272, 2021). "Lastly, the proteomic content of plasma EVs isolated from HIV-infected individuals with T2D, was at top related to metabolic and cardiovascular disease genes and upstream regulation of inflammatory pathways, including IL-6 and inflammasome activation (IL-1β)." (PMID 34754007, 2021). "We focused initially on IL1B in view of its relevance for cardiovascular disease and we used hCASMC where MRTF-A had been overexpressed." (PMID 34671275, 2021). "In this review, we summarize current knowledge on the role of IL-1β in atherosclerotic vascular calcification, and describe the latest results reported in clinical trials evaluating anti-IL-1β therapies for the treatment of cardiovascular diseases." (PMID 34803503, 2021).
cardiovascular disease (continued). "The study was designed to assess the benefit of IL‐1β blockade through application of the anti-IL-1β antibody canakinumab as a secondary prevention strategy in patients with cardiovascular disease." (PMID 33530653, 2021). "The first two members of the IL-1 family—IL-1α and IL-1β—have been extensively studied in cardiovascular disease." (PMID 34884857, 2021). "The potential of attenuating the inflammatory response in cardiovascular diseases has led to studies investigating anti-inflammatory approved anti-IL-1β interventions." (PMID 34207886, 2021). "Inflammation dampens reverse cholesterol transport (RCT) and promotes atherogenesis, while anti-IL-1β antibodies were shown to reduce cardiovascular disease in humans." (PMID 34395445, 2021). "Various factors can activate IL-1β production and pyrolysis, enabling the participation of IL-1β in the pathophysiological process of cardiovascular diseases." (PMID 34803503, 2021). "IL-1β triggers many proinflammatory pathways, and among those, the IL-6 signaling pathway has attracted particular attention in the field of cardiovascular diseases." (PMID 33374145, 2020). "Selected compounds showed protection against oxidative stress induced by inflammatory stimuli important in cardiovascular diseases, i.e., Angiotensin II and Interleukin 1β (IL-1β)." (PMID 32854368, 2020). "IL-1β can be used as a potent predictor of incident cardiovascular disease, and the high calcium burden of the coronary artery is positively correlated with the level of serum IL-1β." (PMID 32457633, 2020). "Many hot nodes in the PPI network are inflammatory factors, including IL8, IL1B, CXCL3, CXCL12, and HLA genes, which are associated with cardiovascular diseases." (PMID 30885136, 2019). "Pro-inflammatory IL-1β and corresponding components promote the development of chronic neuropathic pain, metabolic disorders, cardiovascular diseases and neuropsychiatric disorders." (PMID 31217010, 2019). "The stimulatory chain from TNF-α and IL-1b to R/C can also have a pathogenomic effect in cardiovascular diseases." (PMID 30174768, 2018). "For instance, IL-6 is a known downstream target of IL-1β, consistently increased in patients with NLRP3 inflammasome-mediated conditions, such as cardiovascular disease and associated with clinical outcomes." (PMID 30483114, 2018). "In this context, activation of NLRP3 inflammasome mediating IL-1β and IL-18 secretion has emerged as an important component of inflammatory processes in cardiovascular diseases." (PMID 29245937, 2017). "Emergence of IL-1 as a target in cardiovascular disease prompted the investigation of the redundancy of IL-1α and IL-1β in the induction of MMP-3 and other matrix-remodeling enzymes in human cells." (PMID 27032103, 2016). "NLRP3 inflammasomes recognize non-microbial danger signals and induce release of proinflammatory cytokine interleukin (IL)-1β, leading to sterile inflammation in cardiovascular disease." (PMID 27225830, 2016). "One promising anti-inflammatory approach with potential relevance for cardiovascular disease is inhibition of the pro-inflammatory cytokine IL-1β." (PMID 24884602, 2014). "While monoclonal antibodies targeting IL-1α and IL-1β have transformed the management of autoinflammatory, rheumatologic, and cardiovascular disease, their efficacy is often limited by poor tissue penetration, compensatory cytokine networks, and systemic immunosuppression risks." (PMID 42006724, 2026). "Furthermore, IL-1β-related inflammatory responses can accelerate vascular calcification, a critical factor in the pathophysiology of cardiovascular disease." (PMID 39984847, 2025). "IL‐1β antagonism represents a critical therapeutic strategy in cardiovascular disease." (PMID 40462499, 2025). "The pro-inflammatory role of IL-1β in cardiovascular events and its interaction with the anti-inflammatory and immune-regulatory functions of Tregs constitute an important mechanism in the development of cardiovascular diseases." (PMID 38558816, 2024).
cardiovascular disease (continued). "Consequently, immunomodulation targeting IL-1β offers significant protective effects against cardiovascular diseases." (PMID 38558816, 2024). "In fact, previous research has confirmed that EAT participates in the occurrence and progression of cardiovascular diseases by synthesizing and secreting proinflammatory mediators and neurohormones such as IL-1β, IL-6, TNF-α, MCP-1, resistin, visfatin, and others." (PMID 38277087, 2024). "Apart from IL-6 and IL-1β, other inflammatory markers may also play critical roles in cardiovascular diseases." (PMID 39057626, 2024). "IL1β has a well-established pro-inflammatory role in cardiovascular diseases." (PMID 37947656, 2023). "IL-1ra counter-regulates IL-1β, a key cytokine in the development of cardiovascular diseases." (PMID 37174632, 2023). "Elevated IL-1β activity contributes to the pathogenesis of conditions such as insulin resistance, adverse cardiac remodeling, and heart failure and it thus emerged as a therapeutic target, especially for inflammatory, metabolic, and cardiovascular diseases." (PMID 37336361, 2023). "Since inflammatory factors, such as IL1β and IL6, increase risk of cardiovascular diseases, the signaling from ER stress to inflammation induced by the TKIs may be a potential target for treating cardiotoxicity." (PMID 37069550, 2023). "Canakinumab, a monoclonal antibody to human IL-1β, has been shown to suppress tumorigenic inflammatory pathways and angiogenesis in certain types of lung cancers, and is currently under investigation for effects in cardiovascular disease." (PMID 38275364, 2023). "IL-1β and Tie-2 receptors may be important mediators between inflammation and vascular dysfunction in patients with SCZ and may underlie the increased cardiovascular disease in this population." (PMID 37491201, 2023). "Inhibitors that selectively target the formation of the NLRP3 inflammasome, preventing the cleavage of pro-caspase 1, and the downstream effectors (activation of IL-1β) are widely desired and currently in development for the treatment of cardiovascular diseases." (PMID 38068879, 2023). "IL-1β is involved in CSE-induced PAPP-A expression and apoptosis in vascular smooth muscle cells, which might be considered as a target for preventing of cardiovascular diseases caused by cigarette smoking." (PMID 36791122, 2023). "IL-18 and IL-1β expressed by VSMCs play important roles in cardiovascular disease." (PMID 36527086, 2022). "IL-1β is an inflammatory cytokine that enhances the expression of numerous proinflammatory cytokines, and monoclonal antibodies that target IL-1β may protect against cardiovascular disease." (PMID 36501095, 2022). "Also, in a randomized double-blind clinical trial, CANTOS, a significant reduction in the number of adverse cardiovascular diseases was demonstrated under the influence of the specific IL-1β blocker, canakinumab." (PMID 35242141, 2022). "In the context of cardiovascular disease, and atherothrombosis in particular, IL-1α and IL-1β may subserve distinct functions." (PMID 33924019, 2021). "Antagonizing the action of IL-1β has generated considerable interest in cardiovascular disease." (PMID 33924019, 2021). "Furthermore, IL-6 and IL-1β are both involved in a broad range of other biological activities, regenerative processes, metabolic control, and the prevention of cardiovascular disease." (PMID 34945535, 2021). "IL-1β also plays an important role in the development of cardiovascular diseases." (PMID 34803503, 2021). "It has been reported that simvastatin inhibits IL-6, IL-8 and IL-1β production in vitro, which may contribute to its protective role in cardiovascular diseases." (PMID 33327440, 2020). "This study aimed to investigate the linkage between serum markers of obesity and risk of cardiovascular diseases, with particular reference to the adipokines galectin-3, plasminogen activator inhibitor-1 (PAI-1), IL-1β, CRP, monocyte chemoattractant protein-1 (MCP-1), and insulin." (PMID 32290863, 2020).